MAPT (microtubule associated protein tau)
Diseases named in the same sentence as MAPT in open-access papers (continued):
Sharing a sentence is not in itself a finding about the gene and the disease.
tauopathies (continued). "Here, we demonstrate that MAPT p.R406W is sufficient to induce changes in GABA-mediated signaling and synaptic function, which may contribute to the pathogenesis of FTLD-tau and other primary tauopathies." (PMID 30546007, 2018). "Such a scenario exists in post-encephalitic parkinsonism, a 3R/4R tauopathy that may be attributed to post-viral encephalitis, in which α-synuclein pathology is absent, in PSP, and in parkinsonism due to specific MAPT mutations." (PMID 28386764, 2017). "However, in the brains of individuals who died with the primary tauopathies progressive supranuclear palsy (PSP) and frontotemporal dementia caused by the MAPT 10+16 mutation, we did not observe increased microglial engulfment, and increased astrocytic engulfment was only observed in PSP." (PMID 40790741, 2025). "Interestingly, mutations in the MAPT gene encoding tau protein are not linked to AD, but to frontotemporal dementia (FTD) and other tauopathies, a term that comprehends a wider range of neurodegenerative disorders in which deposits of tau are found in the brain." (PMID 32967303, 2020). "The fact that STH is known to bind MAPT makes it of direct interest in relation to MAPT interactions, and the observation that complete single exon ORF STH may exist only in hominoids is noteworthy because monkeys appear much less prone to tauopathies and clinical features of Alzheimer’s." (PMID 27030133, 2016). "Similarly to other tauopathies, such as progressive supranuclear palsy (PSP) and corticobasal degeneration (CBD), CSF Tau and p-Tau levels were not elevated in individuals with pathogenic variants in MAPT indicating that Tau levels do not serve as a biomarker for MAPT-associated FTD." (PMID 34561610, 2021). "In our cohort, there were cases with relatively higher levels of tauopathy in the NA and ATN but lower levels of fornix p-MAPT that contributed to this lack of correlation." (PMID 27793193, 2016). "Although a genetic interaction between Bin1 and MAPT has been shown in Drosophila and the corresponding proteins have been described to physically interact, the impact of BIN1 expression levels on cognitive function has not yet been investigated in a mammalian tauopathy model." (PMID 31065832, 2019).
frontotemporal dementia (456 papers, 2004 to 2026). Frontotemporal dementia (FTD) comprises a group of neurodegenerative disorders, characterized by progressive changes in behavior, executive dysfunction and language impairment, as a result of degeneration of the medial prefrontal and frontoinsular cortices. "When the tau‐encoding MAPT gene on chromosome 17 is mutated, it results in FTD with parkinsonism (FTDP‐17) as the tau protein LLPS is promoted." (PMID 40599234, 2025). "Robust NFT, neurodegeneration, atrophy, and motor deficits are typically achieved with transgenic overexpression of mutations on the MAPT gene (P301L, P301S) that cause frontotemporal lobar degeneration (FTLD)." (PMID 40269912, 2025). "Frontotemporal dementia is linked to mutations in the microtubule-associated protein tau (MAPT), progranulin (GRN), and chromosome 9 open reading frame 72 (C9orf72) genes." (PMID 41194168, 2025). "Mutations in microtubule-associated protein Tau (MAPT), the gene that codes for the protein Tau, cause frontotemporal lobar degeneration (FTLD) with phenotypes ranging from behavioral changes to cognitive impairment and parkinsonism." (PMID 41318029, 2025). "Autosomal dominant mutations in MAPT encoding for microtubule-associated Tau proteins are responsible for frontotemporal lobar degenerations (FTLD-Tau)." (PMID 40319030, 2025). "Background and objectives: Frontotemporal dementia (FTD) is a heterogeneous neurodegenerative disorder with autosomal dominant forms most often linked to MAPT, GRN, and C9orf72." (PMID 41149783, 2025). "As a model to study mitochondrial dysfunction, we selected neuronal cells derived from iPSCs of a patient with frontotemporal dementia with parkinsonism-17 carrying the pathogenic mutation c.2013T > G (p.N279K) in the MAPT gene." (PMID 40149527, 2025). "Even among relatives carrying the same mutation (e.g., MAPT P301S), clinical presentations can vary, with some individuals exhibiting parkinsonism as the earliest manifestation while others primarily develop frontotemporal dementia." (PMID 41318029, 2025). "Pathogenic mutations in MAPT have been shown to cause some forms of frontotemporal dementia (FTD), a group of diseases characterized by deficits in behaviour, language or movement." (PMID 40349043, 2025). "It is well-established that mutations in MAPT are relevant to a type of frontotemporal dementia associated with parkinsonism." (PMID 39596513, 2024). "While there are no reports of loss-of-function mutations of the APache gene in AD patients, its transcription was significantly reduced in frontotemporal lobar degeneration associated with the MAPT p.R406W mutation and supranuclear palsy." (PMID 39367928, 2024). "Dominantly inherited mutations in MAPT cause a form of frontotemporal dementia that can be associated with parkinsonism (FTDP‐17T)." (PMID 37746832, 2024). "This was used in patient-derived iPSCs to modify alternative splicing in the MAPT gene, aiming to counteract pathogenic mutations associated with Frontotemporal dementia and parkinsonism linked to chromosome 17 (FTDP-17)." (PMID 39086926, 2024). "We modeled pathogenic tau by using human iPSC-derived neurons with the MAPT V337M mutation, a known cause of frontotemporal dementia." (PMID 38895329, 2024). "Then, in June 1998, mutations in MAPT were linked to a type of frontotemporal dementia associated with parkinsonism." (PMID 38073060, 2024). "We present an in-depth clinical and neuroimaging analysis of a family carrying the MAPT K298E mutation associated with frontotemporal dementia (FTD)." (PMID 38592608, 2024). "Pathogenic variants in the MAPT gene itself cause frontotemporal dementia (FTD), sometimes with parkinsonism, and primarily occur in exons 9–13 that make up the MTBR." (PMID 37832941, 2024). "In the EOPSP patients, 4 of 6 had microtubule associated protein tau (MAPT) and non‐MAPT frontotemporal dementia‐related genes tested in a standard dementia panel." (PMID 39113437, 2024).
frontotemporal dementia (continued). "Missense mutations in the gene encoding the microtubule-associated protein TAU (current and approved symbol is MAPT) cause autosomal dominant forms of frontotemporal dementia." (PMID 38599684, 2024). "CMA also degrades proteins associated with Alzheimer’s disease and frontotemporal dementia, such as MAPT (Tau), TARDBP, and APP." (PMID 39687864, 2024). "iPSCs were used to correct a deficiency in a 59-year-old female patient with frontotemporal dementia and parkinsonism who was carrying an R406W mutation in the microtubule-associated protein tau (MAPT) gene." (PMID 39768017, 2024). "A dominantly inherited form of frontotemporal dementia and parkinsonism was found to be associated with chromosome 17q21–22, the region where MAPT resides." (PMID 38073060, 2024). "MAPT variants are a known cause of frontotemporal dementia and Parkinsonian syndrome, of which progressive supranuclear palsy syndrome (PSP) is a rare manifestation." (PMID 38708005, 2024). "A dominantly inherited form of frontotemporal dementia and parkinsonism was found to be associated with chromosome 17q21–22, the region where MAPT is located." (PMID 39596513, 2024). "Mutations in the microtubule-associated protein Tau (MAPT) gene that increases the aggregation of Tau protein have been linked to frontotemporal dementia and parkinsonism in the chromosome 17 (FTDP-17)." (PMID 37450931, 2024). "In 1998, mutations in MAPT, the gene that encodes tau, were identified as the cause of a dominantly inherited form of frontotemporal dementia with abundant filamentous tau inclusions." (PMID 38073060, 2024). "Early pathological features of frontotemporal lobar degeneration (FTLD) due to MAPT pathogenic variants (FTLD-MAPT) are understudied, since early-stage tissue is rarely available." (PMID 37533060, 2023). "We have previously shown that the presence or absence of a specific SVA element, termed SVA_67, was associated with differential expression of several genes at the MAPT locus, a locus associated with Parkinson’s Disease (PD) and frontotemporal dementia." (PMID 37840928, 2023). "First, most of these animal models frequently rely on an overexpression of human tau protein (huTau) with disease‐related mutations, for example, P301L and R406W in FTLD‐MAPT (frontotemporal lobar degeneration associated with MAPT mutations)." (PMID 37013265, 2023). "In 1998, mutations in the MAPT gene were first described as a cause of dementia linked to tau pathology, which was named frontotemporal dementia and parkinsonism linked to chromosome 17 (FTDP-17)." (PMID 36707904, 2023). "We conclude that mutation ∆K281 in MAPT causes an inherited form of Pick’s disease, with neurons and glial cells containing filaments with the Pick fold of 3R Tau." (PMID 37351604, 2023). "Frontotemporal dementia (FTD) is a heritable disease caused by MAPT mutations that result in the accumulation of tau and glutamatergic cortical neuronal death." (PMID 37146581, 2023). "MAPT encodes the tau–protein which misfolds and forms a hallmark of frontotemporal dementia and Alzheimer’s disease." (PMID 37709755, 2023). "The R406W variant in MAPT causes frontotemporal dementia with parkinsonism-17, an autosomal-dominant, neurodegenerative disorder with tau pathology (i.e., tauopathy)." (PMID 37219079, 2023). "A novel variant in MAPT resulting in an alanine-to-threonine substitution at position 152 (A152T tau) has recently been described as a significant risk factor for both frontotemporal lobar degeneration and Alzheimer’s disease." (PMID 40729198, 2023). "When incubated with ligands HS-84 and bTVBT4, case 1 with MAPT mutation ∆K281 behaved in the same way as a case of Pick’s disease." (PMID 37351604, 2023). "Frontotemporal dementia is caused due to mutations in the microtubule-associated protein tau (MAPT), an identified risk component for advancing supranuclear palsy and corticobasal deterioration." (PMID 36909056, 2023).
frontotemporal dementia (continued). "Deposition of tau amyloids in frontotemporal dementia-tau (FTD-tau) is linked to mutations in the microtubule-associated protein tau gene (MAPT) that often localize to the repeat domain and in proximity to amyloid motifs." (PMID 36797278, 2023). "We now show that mutation ∆K281 in MAPT causes an inherited form of Pick’s disease, indicating that relative overproduction of 3R Tau is sufficient to give rise to the Pick fold." (PMID 37351604, 2023). "Autosomal dominant mutations in the MAPT gene encoding for Tau lead to a relatively small group of frontotemporal lobar degenerations (FTLD-Tau), which are classified among frontotemporal dementia diagnosed mostly at 45–65 years of age." (PMID 37842084, 2023). "Lastly, P301S aggTau was used in this study, as it is one of the mutations in human MAPT gene that leads to early onset frontotemporal dementia and manifests the neuropathological features of hyperphosphorylated tau." (PMID 36139003, 2022). "Researchers identified mutations in the MAPT gene in over 150 families with frontotemporal lobar degeneration." (PMID 36361631, 2022). "In 1998, three missense mutations and three mutations in the 5′-splice site of exon 10 in MAPT were identified in large Dutch kindred with hereditary frontotemporal dementia." (PMID 35720097, 2022). "Transgenic mouse lines bearing MAPT mutations have, therefore, been used to mimic human frontotemporal lobar degeneration." (PMID 35682712, 2022). "To study important genes involved in Frontotemporal Dementia (MAPT,GRNandC9orf72), we created deletion alleles in the three orthologous genes (ptl-1,pgrn-1, andalfa-1)." (PMID 36204657, 2022). "This locus contains several genes including MAPT in which mutations can cause, or polymorphisms are correlated with the neurodegenerative diseases frontotemporal dementia (FTD) with parkinsonism and progressive supranuclear palsy (PSP)." (PMID 35370538, 2022). "The microtubule‐associated protein tau gene (MAPT) 10+16 intronic mutation causes frontotemporal lobar degeneration (FTLD) by increasing expression of four‐repeat (4R)‐tau isoforms." (PMID 34951131, 2022). "Aggregation of the microtubule-associated protein tau characterizes tauopathies, including Alzheimer's disease and frontotemporal lobar degeneration (FTLD-Tau)." (PMID 36533443, 2022). "Following this report, key studies identified mutations in MAPT, and linked them to familial forms of frontotemporal dementia with parkinsonism." (PMID 35314000, 2022). "MAPT encodes the microtubule-associated protein tau (MAPT), which promotes microtubule assembly and stability and was associated with frontotemporal dementia." (PMID 35168626, 2022). "One of the most typical MAPT‐related disorders is frontotemporal dementia with parkinsonism linked to chromosome 17, which is caused by MAPT mutations." (PMID 38868661, 2022). "Mutations in MAPT cause neurodegenerative tauopathies, e.g. progressive supranuclear palsy and frontotemporal dementia." (PMID 35179198, 2022). "A third of frontotemporal dementia (FTD) is caused by an autosomal-dominant genetic mutation in one of three genes: microtubule-associated protein tau (MAPT), chromosome 9 open reading frame 72 (C9orf72) and progranulin (GRN)." (PMID 35348856, 2022). "Nearly all cases of frontotemporal lobar degeneration (FTLD) are driven by microtubule-associated protein tau (MAPT), TDP-43 or the fused-in-sarcoma (FUS) protein accumulation." (PMID 35273561, 2022). "A familial form of FTD was identified in 1994 linked to the MAPT gene on chromosome 17, which was later named frontotemporal dementia, and parkinsonism linked to chromosome 17 (FTDP-17) due to its similar clinical, neurological, and genetic profile." (PMID 34458044, 2021). "This region encompasses several genes and includes MAPT in which mutations can cause the neurodegenerative diseases frontotemporal dementia with parkinsonism and progressive supranuclear palsy." (PMID 34035310, 2021).
frontotemporal dementia (continued). "Transgenic mice bearing the MAPT P301 mutation are commonly employed to mimic human frontotemporal lobar degeneration." (PMID 34575885, 2021). "More strikingly, frontotemporal lobar degeneration caused by MAPT (microtubule-associated protein tau) mutations has been found to exhibit mitotic defects that lead to neuronal aneuploidy and apoptosis in the diseased brain." (PMID 34069648, 2021). "Mutations in microtubule associated protein tau gene and the gene encoding progranulin are specific for frontotemporal dementia." (PMID 34635138, 2021). "PHF are not characteristic of only AD and have been characterized in frontotemporal dementia (FTD) linked to a V337M MAPT mutation as well as D252V and G389_I392del mutations." (PMID 34122554, 2021). "In this cohort study of 232 patients with genetic frontotemporal dementia, patients with MAPT variants showed the highest frequency and severity of most behavioral symptoms compared with C9orf72 and GRN carriers." (PMID 33404617, 2021). "A mutation in the MAPT gene that causes a P301S substitution in tau results in the early onset of familial frontotemporal dementia with parkinsonism linked to chromosome 17." (PMID 33397489, 2021). "C>G substitution at position +19 in exon 10 of microtubule-associated protein tau MAPT gene affects splicing of mutually exclusive exons and causes frontotemporal dementia with Parkinsonism linked to chromosome 17 (FTDP-17)." (PMID 32951567, 2021). "Various missense, silent and intronic MAPT mutations cause familial forms of frontotemporal dementia with parkinsonism and these mutations are associated with tau hyperphosphorylation, MT dysfunction, and aggregation." (PMID 34090488, 2021). "PS19 mice bearing the MAPT P301S mutation have been used to mimic human frontotemporal lobar degeneration." (PMID 34575885, 2021). "In frontotemporal dementia, different mutations in the MAPT gene associated with chromosome 17 cause various clinical presentations." (PMID 32079163, 2020). "Genetic mutations in the MAPT gene encoding for TAU protein cause an inherited form of frontotemporal dementia, a neurodegenerative disorder, but also increase the risk of developing cancer." (PMID 33207722, 2020). "For comparative purposes, we also analysed one sporadic GGT presenting with primary progressive aphasia [case 1, 38], and another genetic GGT case manifested with frontotemporal dementia, parkinsonism, and motor neuron disease linked to K317M mutation in MAPT." (PMID 31907603, 2020). "Frontotemporal dementia astrocytes, derived from iPSCs with mutations in genes encoding microtubule-associated protein TAU (MAPT) and TDP-34, demonstrated an increased susceptibility to oxidative stress and compromised survival." (PMID 30809131, 2019). "In humans with frontotemporal dementia caused by the P301L mutation in MAPT, only protein produced from the mutant allele was found in Tau inclusions." (PMID 30885267, 2019). "The identification of disease-causing mutations in MAPT, the Tau gene, in cases of frontotemporal dementia, showed that dysfunction of Tau protein is sufficient to cause neurodegeneration and dementia." (PMID 30885267, 2019). "Autosomal-dominant mutations in MAPT cause inherited frontotemporal dementia (FTD), but the underlying pathogenic mechanisms are unclear." (PMID 30650353, 2019). "The present study aimed to analyze clinical profiles, tau accumulations, and their correlations in 3 kindreds with frontotemporal dementia and parkinsonism linked to chromosome 17 attributed to the MAPT N279K mutation." (PMID 30773680, 2019). "Cases of frontotemporal dementia are caused by dominantly inherited mutations in MAPT, the Tau gene." (PMID 29497399, 2018). "The identification of some families bearing highly penetrant, dominant mutations within the MAPT gene causing frontotemporal dementia demonstrated that tau dysfunction is sufficient to cause neurodegeneration and dementia." (PMID 29641484, 2018).